TREM1 (triggering receptor expressed on myeloid cells 1)
Diseases named in the same sentence as TREM1 in open-access papers (continued):
Sharing a sentence is not in itself a finding about the gene and the disease.
Sepsis (continued). "In experimental sepsis models, Nrf2-knockout mice exhibit heightened NFκB activation in response to LPS stimulation compared to control mice, further supporting the role of PG-induced Nrf2 activation in suppressing TREM-1 expression." (PMID 41226426, 2025). "To summarize, in early sepsis, TREM-1 levels rise on monocytes and neutrophils." (PMID 41226426, 2025). "A new multi-center prospective clinical study identified TREM-1 as a good indicator for the diagnosis of sepsis-associated AKI in patients; however, no research has been conducted regarding the function of TREM-1 in AKI-induced lung injury." (PMID 41227360, 2025). "As sepsis worsens, surface TREM-1 declines while -sTREM-1 increases." (PMID 41226426, 2025). "In sepsis, infections and inflammations are mistakenly used synonymously, although they are not mutually exclusive; however, their markers, e.g., cytokines, chemokines, presepsin, and TREM-1, are shared." (PMID 39857101, 2025). "Additionally, the presence of circulating TREM-1 ligands in sepsis patient sera has been demonstrated using the TREM-1-Fc fusion protein." (PMID 41226426, 2025). "Indeed, researchers recently published the interesting results of a phase 2b trial in which patients with sepsis were treated with nangibotide, a TREM-1 inhibitor." (PMID 38191420, 2024). "TREM1-mediated neuroinflammation has been shown to be involved in the pathophysiological processes of ischaemic stroke, subarachnoid haemorrhage, myocardial infarction, inflammatory bowel disease, and sepsis." (PMID 38177990, 2024). "In addition, eCIRP also functions as a new biologically active endogenous ligand of triggering receptor expressed on myeloid cells‐1 (TREM‐1) that incites inflammation in sepsis." (PMID 39400399, 2024). "In an early study, researchers reported an unknown ligand expressed on platelets that activates TREM-1 in sepsis." (PMID 38191420, 2024). "eCIRP upregulates BMAL2 expression via TREM-1, leading to macrophage endotoxin tolerance in sepsis." (PMID 38938563, 2024). "In hemorrhagic shock and sepsis, TREM-1 can also be a key target of eCIRP." (PMID 36865547, 2023). "Our group and others have developed a pharmacological TREM-1 blocker, LR-12, which has been shown to provide benefits in experimental chronic diseases, including atherosclerosis and aortic aneurysm, as well as in acute injury, including sepsis and acute MI." (PMID 37522081, 2023). "In the discovery of HSPA12B and TREM-1, besides measuring the changes of candidate biomarkers in mouse sepsis, the disease severity of mouse sepsis, either controlled by the CLP puncture numbers or monitored by bacterial loads, was used to analyse the correlation with candidate biomarkers." (PMID 37456011, 2023). "After it was determined that an unknown ligand expressed on platelets activates TREM-1 in sepsis, further investigation using gel analysis of platelet total protein and rTREM-1 suggested the ligand to be actin." (PMID 35784361, 2022). "It was also reported that the levels of secretory TREM-1 (sTREM-1) in both serum and urine showed higher sensitivity than white blood cell count, C-reactive protein, and procalcitonin in the early recognition of sepsis." (PMID 35619710, 2022). "Since then, multiple ligands have been implicated as activators of TREM-1, furthering our knowledge on this receptor’s role in innate immunity, sepsis, and non-infectious inflammatory diseases." (PMID 35784361, 2022). "TREM-1 was significantly highly expressed in bacterial-induced sepsis patients (p < 0.01)." (PMID 36110326, 2022). "Additionally, TREM-1/Fc provided protection in mice against sepsis after intravenous (i.v.)injection of Streptococcus pyogenes." (PMID 35784361, 2022). "In addition to being studied as a prognostic indicator of sepsis severity, it has also been proposed to act as a decoy receptor for TREM-1 by binding its ligands and reducing its activation and the subsequent pro-inflammatory cytokine release." (PMID 35784361, 2022).
Sepsis (continued). "As reported, TREM-1 are upregulated in sepsis to severe as mediators of inflammation." (PMID 36110326, 2022). "We demonstrated that TREM-1 was upregulated in sepsis patients and in vivo models." (PMID 36110326, 2022). "Therefore, this review encompasses the ligands investigated as activators of TREM-1 thus far and highlights the development and efficacy of novel inhibitors for the treatment of sepsis and septic shock." (PMID 35784361, 2022). "There are several studies reporting that TREM1 plays a role in sepsis." (PMID 33525982, 2021). "In sepsis, β-actin can interact with TREM-1 on platelets to enhance the inflammatory response." (PMID 34959583, 2021). "TREM1 plays an important regulatory role in the innate immune response, and early research has focused primarily on the role of TREM1 in lipopolysaccharide-induced sepsis." (PMID 33829052, 2021). "Following initial findings of elevated TREM-1 levels in infectious conditions such as sepsis, studies reported its upregulated membrane expression, as well as elevated blood and body fluid levels of sTREM-1, also in various noninfectious inflammatory conditions." (PMID 33814983, 2021). "TREM-1 could not only mediate sepsis-related kidney damage but also contribute to inflammation in IgA nephropathy, which has been detected by urinalysis." (PMID 33390769, 2021). "Collectively, secreted WARS1 may represent an expected sepsis drug target at the apex of the TLRs/TREM-1 signaling cascade." (PMID 32899943, 2020). "TREM-1 is expressed mainly on monocytes/macrophages and neutrophils and is recognized as a novel receptor, which participates in the amplification of inflammatory responses in sepsis." (PMID 32825174, 2020). "We hypothesize that the eCIRP/TREM-1 interaction in cardiomyocytes contributes to sepsis-induced cardiac dysfunction in neonatal sepsis, while M3 is cardioprotective." (PMID 33276725, 2020). "Both eCIRP and TREM-1 are upregulated in sepsis to serve as mediators of inflammation." (PMID 33276725, 2020). "Collectively, WARS1-mediated TREM-1 could be an attractive target for sepsis treatment owing to its ability to modulate innate immune responses." (PMID 32899943, 2020). "TREM-1 was identified as a key player of hyper-inflammation in sepsis." (PMID 32899943, 2020). "Interestingly, LR17 reduced TREM-1 expression in both the initial and later stages of sepsis and decreased the detrimental effects of the chronic inflammation in mice models of sepsis, thus increasing their chances of survival." (PMID 30205488, 2018). "During sepsis TREM-1 expression is enhanced and released in a soluble form (sTREM-1)." (PMID 30018308, 2018). "Several clinical studies have suggested a specific role of TREM-1 in pneumonia and sepsis." (PMID 29844416, 2018). "Due to its key role on enhancement of the inflammatory response, TREM-1 was recognized as an important regulator of innate immunity in sepsis, septic shock, autoimmune arthritis, chronic inflammatory disorders, inflammatory bowel disease, and corneal inflammation." (PMID 29619033, 2018). "Interestingly, it has recently been found that MMP-9 has a pivotal role in cleaving the membrane-bound, TREM-1-inducing, increased circulation of sTREM-1 above the threshold, so that it is used as important biomarker in sepsis." (PMID 30205488, 2018). "Therefore, extracellular actin is a new ligand for TREM-1 during sepsis, and the present study provides a link between both essential regulators of death in sepsis." (PMID 28824642, 2017). "Therefore, the present study identified actin as a new ligand for TREM-1 signaling, and it also provided a link between both essential regulators of death in sepsis." (PMID 28824642, 2017). "However, both cell surface TREM-1 and sTREM-1 are up-regulated during sepsis: due to the undemanding method required to dose the soluble form, this protein has been proposed for the diagnosis of infection in the clinical setting." (PMID 27116911, 2016).
Sepsis (continued). "However, a significant reduction in the expression of TREM-1 on PMNs during sepsis was noticed, with a sensitivity of 56.2 % and a specificity of 93.7 %." (PMID 27116911, 2016). "Early studies reported a role for TREM-1 in sepsis models and found that soluble TREM-1 could serve as a biomarker for acute inflammation during infection." (PMID 27083877, 2016). "TREM-1 has been suggested as a biomarker for sepsis and melioidosis." (PMID 27253382, 2016). "Trem1 is a pro-inflammatory mediator that amplifies endotoxin-induced shock in sepsis." (PMID 27141827, 2016). "While TREM1 is constitutively expressed by myeloid cells, the level of induction influences the outcome of infection, such that in a mouse model of sepsis, moderate silencing of TREM1 improved survival, but near-complete silencing reduced neutrophil oxidative burst and increased mortality." (PMID 26133770, 2015). "TREM-1 has been identified as an important cell surface molecule involved in sepsis." (PMID 25944130, 2015). "TREM1 gene, which is an important sepsis marker, was elevated in serovar L2 infected monocytes." (PMID 25123797, 2014). "In addition, recombinant TREM-1/Fc fusion proteins or antagonistic peptides rescue mice from endotoxemia or polymicrobial sepsis." (PMID 25347935, 2014). "This study sought to understand the complex expression of TREM-1 on monocytes in sepsis." (PMID 25532536, 2014). "Current evidence suggests that TREM-1/sTREM-1 may be an important player in the pathogenesis of sepsis." (PMID 24350219, 2013). "Since Trem-1 has been discussed as a potential therapeutic target in sepsis, the precise role in inflammatory response to bacterial infection of soluble and surface bound Trem-1 on neutrophils and monocytes should be further evaluated in clinical and experimental studies." (PMID 23414215, 2013). "However, gene expression of TREM-1 was up-regulated in circulating monocytes of patients experiencing severe sepsis." (PMID 24350219, 2013). "A correlation between soluble Trem-1 and sepsis severity has also been shown in recent papers." (PMID 23414215, 2013). "The number of TREM-1 gene transcripts was similar between severe sepsis and septic shock." (PMID 23861562, 2013). "Expression of TREM-1 was compared with patients with systemic inflammatory response syndrome of non-infectious origin and no data were available for patients at the stages of sepsis and of severe sepsis." (PMID 22050935, 2011). "The present study provides further insight in the modulation of TREM-1 expression in sepsis." (PMID 22050935, 2011). "Among patients who suffered infections by Gram-negative community-acquired pathogens or among patients who suffered polymicrobial infections, expression of TREM-1 on monocytes was significantly lower at the stage of severe sepsis/shock than at the stage of sepsis." (PMID 22050935, 2011). "TREM-1, too, is induced on the surface of activated macrophages and neutrophils, and has been shown to play important roles in the systemic manifestations of sepsis." (PMID 18522745, 2008). "Current evidence suggests that TREM-1 levels could represent a valuable marker of infection in several pathological conditions including sepsis." (PMID 18628981, 2008). "Although the cellular signaling events downstream of TREM-1 engagement are incompletely understood, recently reported data suggest that receptor expression is essential for mounting an adequate inflammatory and cytotoxic response to polymicrobial sepsis." (PMID 18628981, 2008). "TREM-1 is also produced in a soluble form and released in humans after endotoxin exposition or in patients suffering from severe pneumonia or sepsis." (PMID 18317529, 2007). "TREM-1 inhibitory peptides/proteins, discussed in detail below, are molecules designed to suppress TREM-1 signaling and mitigate excessive inflammatory responses associated with various diseases, including sepsis, ischemia–reperfusion injury, rheumatoid arthritis, and cancer." (PMID 41226426, 2025).
Sepsis (continued). "sTREM-1 as an indicator of TREM-1 activation alongside markedly increased cytokine release could select those patients who would benefit the most from targeted anti-inflammatory or cytokine-reducing therapy—not only in sepsis, but also in other diseases." (PMID 38191420, 2024). "Therefore, there have been substantial efforts to develop TREM-1 inhibitors to treat sepsis." (PMID 38191420, 2024). "Therefore, we detected soluble triggering receptor expressed on myeloid cells (TREM1), a sepsis marker and the indicators of acute kidney injury, neutrophil gelatinase-associated lipocalin (NGAL), serum creatinine (sCr) and blood urea nitrogen (BUN) in serum of mice." (PMID 38566195, 2024). "Further, maortas and mesenteric arteries isolated from TREM-1−/− mice were protected from vascular dysfunction after stimulation with neutrophil extracellular traps (NETs), nuclear DNA expelled from activated neutrophils that propagate the inflammatory response in sepsis." (PMID 36246143, 2022). "Therefore, inhibition of TREM1 can improve the inflammatory state in sepsis." (PMID 33954188, 2021). "Moreover, the levels in sepsis could reflect an essential immune dysfunction, where excessive cleavage of TREM-1 could contribute to immunosuppression and death during severe infection." (PMID 34960790, 2021). "Similarly, our previous studies indicated that a significantly greater reduction of NF-κB activity, neutrophil chemotaxis, and TREM-1 and p38 mitogen-activated protein kinase activity and pulmonary endothelium leakage in sepsis-induced ALI was observed in the iPSC-CM group versus the iPSCs group." (PMID 34074039, 2021). "Because of the role of the TREM-1 pathway in the development of a dysregulated inflammatory response in some patients, it is thought that the pathway could contribute to poor outcomes in sepsis and COVID-19." (PMID 34195785, 2021). "Moreover, TREM1-related NETs formation was found in sepsis and intestinal inflammation." (PMID 34721438, 2021). "TREM-1 pharmacological inhibition may thus reduce the increase in NETs that promotes hyperinflammation, thereby decreasing vascular dysfunction, organ injury, and mortality in sepsis." (PMID 33420354, 2021). "Furthermore, despite some evidence that soluble TREM-1 may be a biomarker for neonatal sepsis, in neonates with sepsis, TREM-1 upregulation is decreased compared to older infants, children, and adults." (PMID 33276725, 2020). "An increase in soluble TREM-1 (sTREM-1) has been described for sepsis patients, where levels could predict survival rates in sepsis better than PCT or CRP, were a good assessment for the prognosis of positive blood cultures and noted as reliable biomarker for sepsis." (PMID 26263001, 2015). "Thus, TREM-1 might be a therapeutic target for the treatment of cardiovascular dysfunction in sepsis." (PMID 24959004, 2014). "Activation of membrane-bound TREM-1 promoted proinflammatory signaling, inducing cytokines such as interleukin 6 (IL-6), TNF-α, and IL-8, as demonstrated in models of sepsis and inflammatory bowel disease." (PMID 41273150, 2026). "TREM-1-Fc-protein: The TREM-1-Fc fusion protein functions as a TREM-1 neutralizing agent, and it has been used to detect the presence of TREM-1 ligands in sepsis patient sera." (PMID 41226426, 2025). "Literature validation yielded 30 ultra-high confidence therapeutic candidates, including both established sepsis genes (IL10, TREM1, S100A9, NLRP3) and novel targets warranting investigation." (PMID 41071041, 2025). "Among the most promising TREM-1 inhibitors, LR12 peptide has shown significant survival benefits in animal models of sepsis and is currently undergoing Phase 2 clinical trials." (PMID 41226426, 2025). "Co-localization studies using confocal immunofluorescence microscopy have confirmed that actin binds to TREM-1 on platelets, further supporting its role as a TREM-1 ligand in sepsis models." (PMID 41226426, 2025).
Sepsis (continued). "Survival of mice with sepsis induced after cecal ligation and puncture (CLP) was prolonged when treated with a peptide that inhibits extracellular cold RNA-binding protein–TREM-1 interaction." (PMID 40007937, 2025). "This open avenues for more research on the application of peptides to target other sepsis inflammatory-microenvironment’s overexpressed components such as selectins, CD44, TREM-1, and protease-activated receptor-1 (PAR-1)." (PMID 38637839, 2024). "In addition, despite the exciting results of nangibotide, the other TREM-1 inhibitors should also be further developed and brought into clinical trial phase in order to test and develop other substances beside nangibotide in the treatment of sepsis and septic shock." (PMID 38191420, 2024). "In this review, we critically address the role of TREM-1 as an important PRR in the development and pathogenesis of inflammation and sepsis." (PMID 38191420, 2024). "The role of SYT13 in sepsis still unknown, whereas TREM1 is a crucial mediator of septic shock that acts by synergizing with Toll-like receptors (TLRs) to amplify the inflammatory responses to pathogens, thus promoting sepsis-induced immune dysregulation and organ dysfunction." (PMID 38283341, 2023). "GF9 is a peptide that inhibits TREM-1 through DNAX-activating protein 12 kD (DAP12), with a concomitant reduction of inflammatory mediators in sepsis." (PMID 36110326, 2022). "After confirming TREM-1’s expression on vascular endothelial cells, the effects of LR12 on vascular reactivity during sepsis was explored." (PMID 35784361, 2022). "Previous studies suggested that triggering receptor expressed on myeloid cells-1 (TREM-1), IL-27, neutrophil CD64, preprotease, and cell-free plasma DNA (cfDNA) were new promising biomarkers for sepsis diagnosis and therapy." (PMID 36457745, 2022). "The expression level of TREM-1, TNF-α, and IL-6 in the sepsis model showed a consistent expression trend in sepsis patients." (PMID 36110326, 2022). "Triggering receptor expressed on myeloid cells-1 (TREM-1) regulates inflammation, leads to immune response, and is a new biomarker for sepsis." (PMID 36110326, 2022). "Using both CLP-sepsis and LPS endotoxemia, it was determined that LR12 prevents the TREM-1 upregulation induced in the murine aortas and mesenteric arteries of mice subjected to these models." (PMID 35784361, 2022). "Overall, all the patients presented with elevated TREM-1 and OPN and most had elevated NGAL and leptin levels; for all, a gradual decrease upon resolution of sepsis was observed." (PMID 34659208, 2021). "Whole blood from patients with simple sepsis showed a higher expression of TREM-1 and higher levels of IL-6, IL-8, IL-10 and TNF-α upon stimulation with LPS when compared with whole blood from patients with severe sepsis." (PMID 33924130, 2021). "Results showed that TNF, HSPA1A, HSPA1B, TREM1, SOD2 and MIF genes related to sepsis correspond to m6A-cis-eQTLs." (PMID 32174955, 2020). "Furthermore, a power calculation to determine a sample size with adequate power at the beginning of the investigation could not be conducted, because the effect of the TREM-1 rs2234237 polymorphism on 90-day mortality in patients with sepsis was unknown." (PMID 30832396, 2019). "In fact, the TREM-1 SCHOOL peptide GF9, in free and HDL-bound form, has shown to be an antitumor and to be able to amend sepsis in experimental models." (PMID 30205488, 2018). "Importantly, extracellular actin could be recognized by TREM-1 during sepsis." (PMID 28824642, 2017). "TREM-1 plays an important role in interaction of monocytes and PMN with platelet and is upregulated in inflammation, severe infection and sepsis." (PMID 27148736, 2016). "TREM-1 and TREM-2 are the most studied members of the TREM-family, however their exact role in the pathogenesis of sepsis remains ill-defined." (PMID 27253382, 2016).